RN7SL665P (RNA, 7SL, cytoplasmic 665, pseudogene)
Gene: Miscellaneous RNA gene on chromosome 9 (130,400,266 to 130,400,565, forward strand). Ensembl gene ENSG00000264169.
Homologues: Orthologues: chimpanzee Metazoa_SRP (99% identical), macaque Metazoa_SRP (92% identical). Paralogues in human: RN7SL1 (86% identical), RN7SL2 (86% identical), RN7SL3 (84% identical), RN7SL45P (84% identical), RN7SL464P (83% identical), RN7SL126P (82% identical), RN7SL122P (81% identical), RN7SL127P (81% identical), RN7SL147P (81% identical), RN7SL586P (81% identical), RN7SL804P (81% identical), RN7SL145P (81% identical), and 702 more.